MYO1F (myosin IF)
Diseases named in the same sentence as MYO1F in open-access papers:
MYO1F is named in the same sentence as 40 diseases in open-access papers, as found by Europe PMC text mining. Sharing a sentence is not in itself a finding about the gene and the disease. The quoted sentences say what the papers report.
colitis (3 papers, 2018 to 2024). Inflammation of the colon. "In a model of colitis, Myo1F deficiency strongly reduces the secretion of proinflammatory cytokines, decreases epithelial damage, ameliorates disease activity, and enhances tissue repair." (PMID 30687322, 2018). "To this end, we investigated the development of colitis mediated by the administration of DSS in Myo1F deficient mice." (PMID 30687322, 2018). "Myo1F deficiency reduces epithelial damage and stimulates recovery in a model of colitis DSS-induced." (PMID 30687322, 2018). "However, DSS treatment induced a more severe colitis in WT than in Myo1F KO mice as shown by weight loss, DAI and histological analysis (greater mucosal ulcerations, increased edema and more infiltration)." (PMID 30687322, 2018). "Consequently, in a model of colitis DSS-induced Myo1F deficiency ameliorated IEC damage and reduced disease symptoms while enhanced epithelial restitution." (PMID 30687322, 2018). "Next, we analyzed Akt, STAT1 and STAT3 in colonic cell lysates of WT and Myo1F−/− animals that were induced to colitis." (PMID 30687322, 2018). "The mechanism by which Myo1F enhances IEC damage during colitis could be directly related to increase in the production/secretion of proinflammatory cytokines by macrophages." (PMID 30687322, 2018). "Therefore, we next analyzed long-term effects of Myo1F depletion in a mouse model of chronic DSS-induced colitis." (PMID 30687322, 2018). "Thus, targeting Myo1F in macrophages appears as good mechanism aimed to reduce the symptoms observed during colitis." (PMID 30687322, 2018). "Thus, taken together all our results support the hypothesis that Myo1F induces M1-polarization in macrophages during colitis by enhancing its intercellular adhesion via integrin-ανβ3 which in turns triggers PI3K/Akt/mTORC1/STAT signaling." (PMID 30687322, 2018). "Thus, in agreement with our previous results these findings strongly suggested that Myo1F deficiency ameliorates the symptoms of DSS-mediated colitis by a mechanism that does not impairs recruitment of monocytes, macrophages and dendritic cells into the inflamed area." (PMID 30687322, 2018). "Thus, our findings suggest that Myo1F enhances activation of Akt and STAT3 signaling in colonic macrophages during colitis." (PMID 30687322, 2018). "In contrast to Myo1F, minimal changes in integrin-ανβ3 and ILK were displayed in the colonic mucosa of control WT and Myo1F−/− mice and both molecules were increased at similar extent after colitis induction in both animals." (PMID 30687322, 2018). "Furthermore, MYO1F upregulation leads to enhanced secretion and production of interleukin-1β and, accordingly, lack of MYO1F has been shown to result in reduced inflammation in a colitis model." (PMID 32272642, 2020). "However, colitis induction failed to stimulate the production of Myo1F in the colonic mucosa of Myo1F−/− animals and also was absent in colonic macrophages of Myo1F−/− colitic mice." (PMID 30687322, 2018).
acute monocytic leukemia (2 papers, 2015 to 2019). Acute monoblastic leukemia (AML-M5), is one of the most common subtypes of acute myeloid leukemia (AML) that is either comprised of more than 80% of monoblasts (AML-M5a) or 30-80% monoblasts with (pro)monocytic differentiation (AML-M5b). "With respect to the role of Myo1f in the immune system, the Myo1f gene has been found to be fused to the mixed lineage leukemia (MLL) gene in acute monocytic leukemia." (PMID 31143189, 2019).
Alzheimer disease (2 papers, 2024 to 2025). A progressive, neurodegenerative disease characterized by loss of function and death of nerve cells in several areas of the brain leading to loss of cognitive function such as memory and language. "In contrast, the gene EPB41L2 (1.079, 1.029 − 1.130, P = .001), MYO1F (1.083, 1.004 − 1.168, P = .039), and SSH2 (1.049, 1.015 − 1.083, P = .004) were associated with a higher risk of developing Alzheimer’s disease." (PMID 39560568, 2024). "Both in humans with Alzheimer's disease (AD) and murine models of AD and frontotemporal dementia/amyotrophic lateral sclerosis (FTD/ALS), MYO1F is significantly upregulated in microglia compared to healthy controls." (PMID 41208482, 2025).
glioma (2 papers, 2022 to 2024). A benign or malignant brain and spinal cord tumor that arises from glial cells (astrocytes, oligodendrocytes, ependymal cells). "Especially, CD300C, CNRIP1 and MYO1F are the top three genes that engage in immune response in the glioma's microenvironment." (PMID 39448550, 2024).
hearing loss (2 papers, 2012 to 2020). "MYO1F (NM_012335.3) has been frequently proposed as a candidate hearing loss gene, because several myosin genes have been demonstrated as causative genes of non-syndromic hearing loss and MYO1F is expressed in cochlea." (PMID 22938506, 2012). "None of these mutations, except the p.I502V mutation in MYO1F, has been identified in previous studies of hereditary hearing loss." (PMID 22938506, 2012).
leukemia (2 papers, 2020 to 2022). A malignant (clonal) hematologic disorder, involving hematopoietic stem cells and characterized by the presence of primitive or atypical myeloid or lymphoid cells in the bone marrow and the blood. "The first half of the MLL protein is placed at the N-terminus of MYO1F, which disrupts MLL function and may lead to increased expression of MYO1F in leukemia cells." (PMID 32670437, 2020). "However, Myo1f is predominantly expressed in cells of the innate immune response, therefore the observed effects have to be evaluated in the context of leukocyte development and leukemia." (PMID 35601920, 2022).
peripheral T cell lymphomas (2 papers, 2019 to 2021). "The presence of the Vav1-Myo1f fusion protein (where the C-terminal SH3 domain of Vav1 is replaced by the SH3 of Myo1f) was recently reported in peripheral T-cell lymphomas (PTLC), a heterogeneous group of non-Hodgkin lymphomas frequently associated with poor prognosis." (PMID 31143189, 2019).
breast carcinoma (1 paper, 2024). "We have not found any prior studies that directly investigate the effect of MYO1F on metastasis, and therefore decided to explore the possible metastasis function of this gene in breast cancer." (PMID 38689334, 2024). "The BMP4 upregulated gene, MYO1F, was shown to be a potent suppressor of breast cancer metastasis." (PMID 38689334, 2024).
colon cancer (1 paper, 2020). "Our results support a hypothesis that transgelin interacts with PARP1 and regulates the expression of downstream key genes (CALM1, MYO1F, NCKIPSD, PLK4, RAC1, WAS and WIPF1), which are mainly involved in the Rho signaling pathway in the human RKO colon cancer cells." (PMID 32774160, 2020).
deafness (1 paper, 2024). An inherited or acquired condition characterized by the complete loss of the ability to hear from one or both ears. "Association of MYO1C and MYO1F variants with deafness was disputed by the ClinGen Hearing Loss Clinical Domain Working Group (CDWG) due to a lack of sufficient functional analyses." (PMID 38562617, 2024). "To date, three genes encoding the class-I myosins, MYO1A, MYO1C and MYO1F, were initially reported as human “deafness genes”." (PMID 38562617, 2024).
fungal infection (1 paper, 2021). "Next, we explored whether there was any defect in local macrophage or neutrophil recruitment in Myo1f-KO mice after fungal infection." (PMID 34301894, 2021). "For a more realistic simulation of fungal infection, we stimulated THP-1 cells with live C. albicans and examined whether MYO1F deficiency had any impact on signaling activation and proinflammatory gene expression." (PMID 34301894, 2021). "Taken together, our findings describe a key role for MYO1F in promoting antifungal immunity by regulating the acetylation of α-tubulin and microtubules, and our findings suggest that Sirt2 deacetylase inhibitors may be developed as potential drugs for the treatment of fungal infections." (PMID 34301894, 2021). "There was a decreased Th17 cell abundance in the lymph nodes of Myo1f-KO mice compared to WT mice after fungal infection, while the abundance of Th1 cells was not different between WT mice and Myo1f-KO mice." (PMID 34301894, 2021).
hyperlipidemia (1 paper, 2019). "All these data demonstrate that NCF2, MYO1F, S1PR4, and FCN1 in PBMC combination with sex and hyperlipidemia could be diagnostic biomarkers for obstructive CAD." (PMID 31245869, 2019). "Subsequent analysis of the diagnostic value of these genes in obstructive CAD further confirmed that NCF2, MYO1F, S1PR4, and FCN1 together with risk factors, gender, and hyperlipidemia, could improve the diagnostic accuracy of distinguishing obstructive CAD from free of obstructive CAD." (PMID 31245869, 2019).
malaria (1 paper, 2025). Malaria is a serious and sometimes fatal disease caused by a parasite that commonly infects a certain type of mosquito which feeds on humans. "Thus, while cMaf is critical for Tfh differentiation in experimental malaria, Myo1f and Prr13, although transcriptionally upregulated, are unnecessary for effector or memory CD4+ T cell responses." (PMID 40132035, 2025). "In this study, we utilised existing scRNA-seq data from a mouse model of blood-stage malaria to hypothesise possible roles for Myo1f and Prr13 in CD4+ T cells." (PMID 40132035, 2025). "Taken together, our analysis revealed Myo1f and Prr13 expression were upregulated and maintained in specific effector and memory CD4+ T cell subsets during experimental malaria." (PMID 40132035, 2025). "Together, our data demonstrated that Myo1f is not required for Th1 differentiation or memory recall in experimental malaria." (PMID 40132035, 2025). "Thus, in summary, we have discovered that cMaf is critical in experimental malaria for the early differentiation of Tfh cells, while Myo1f and Prr13 play no role in the biology of Plasmodium-specific CD4+ T cells during blood-stage infection." (PMID 40132035, 2025).
mastitis (1 paper, 2019). Inflammation of breast tissue during lactation or postpartum due to an obstructed duct or infection. "MYO1F is a possible functional candidate gene for susceptibility to subclinical mastitis and high SCC in Norwegian Red; however, functional studies are required to verify this hypothesis." (PMID 31417606, 2019). "This suggests that low GEBV animals, i.e., those with a higher probability of having high SCC in milk, have increased MYO1F expression that facilitates neutrophil migration to the infected udder during mastitis, which, in turn, may explain high SCC in milk." (PMID 31417606, 2019).
melanoma (1 paper, 2021). A malignant, usually aggressive tumor composed of atypical, neoplastic melanocytes. "More mechanistic studies (e.g., genetic and epigenetic regulation) using immune-competent models are needed to understand the functional impact of the prioritized regulators of melanoma (e.g., MYO1F and ZNF180) on tumor progression and immune modulation." (PMID 33619278, 2021). "We confirmed high MYO1F expression in M1 macrophage populations in the melanoma single-cell transcriptomic data." (PMID 33619278, 2021). "The data also suggest that MYO1F may play a role in mediating interactions between CD8+ T cells and M1-macrophages underlying activated adaptive immune systems in the primary melanoma microenvironment." (PMID 33619278, 2021). "MYO1F mRNA expression was significantly correlated with IFN-γ (i.e., IFNG) in an independent melanoma bulk transcriptomic dataset." (PMID 33619278, 2021). "Given the close interaction between STAT1 and MYO1F (Pearson ρ = 0.32, p = 9.88E − 4), these observations also support the regulatory roles of MYO1F in M1-polarization and STAT1 activation in macrophages, leading to increased IFN-γ secretion in the melanoma microenvironment." (PMID 33619278, 2021).
nonsyndromic deafness (1 paper, 2019). An auditory system disease that is associated with permanent hearing loss caused by damage to structures in the inner ear and/or the middle ear, which is not associated with other signs and symptoms. "Furthermore, Myo1f has been proposed as a candidate gene for nonsyndromic deafness." (PMID 31143189, 2019).
type 1 diabetes mellitus (1 paper, 2019). A chronic condition characterized by minimal or absent production of insulin by the pancreas. "GSEA analysis also revealed that patients with obstructive CAD with higher expression levels of NCF2, MYO1F, S1PR4, and FCN1 in PBMC showed enriched pathways in viral myocarditis, Leishmania infection, type I diabetes mellitus, and hematopoietic cell lineage." (PMID 31245869, 2019).
viral infections (1 paper, 2021). "The functional defects described by the absence of Myo1g and Myo1f could similarly affect NK cells, causing increased susceptibility to viral infections and tumor development." (PMID 34970258, 2021).
tumor (11 papers, 2015 to 2024). "Studies have demonstrated that MYOIF enhances the adhesion and migration of immune cells, promotes M1 polarization of macrophages, and in some tumor patients, MYO1F is mutated to form fusion proteins, promoting tumorigenesis and progression." (PMID 38799454, 2024). "A recent study has shown that mutated MYO1F alters the mitochondrial network and induces tumor proliferation in thyroid cancer." (PMID 32272642, 2020). "Tumor cell expression of MYO1F was increased to a greater degree by BMP4 in the presence of SMAD4 than in its absence." (PMID 38689334, 2024). "Fourteen of the mutated genes in this tumor are involved in metabolism (endogenous molecules as well as drugs), small molecule biochemistry, and cancer: AATF, ATF71P, CRIPAK, CROCC, CYP2A6, DOCK5, GPAT2, KRTAP4–9, LSM14A, MUC2, MYO1F, RHOQ, SUFU, and UTRN." (PMID 29259192, 2017). "What derives from these data is the fact that the MYO1F SH3 domain, possibly by recruitment of proteins, increases the VAV1-dependent tumor activity." (PMID 32272642, 2020). "The presence of MYO1F did not alter primary tumor growth but substantially suppressed metastasis to lung, liver and spine." (PMID 38689334, 2024). "Interestingly, tumor resident ILC1 and NK cells also express Myo1g and Myo1f." (PMID 34970258, 2021).
cancer (8 papers, 2015 to 2024). A tumor composed of atypical neoplastic, often pleomorphic cells that invade other tissues. "How MYO1F regulates the mitochondrial network needs to be addressed.Several somatic mutations in MYO1F related to different types of cancer have been found in genetic databases." (PMID 32272642, 2020). "At first glance, our data seemingly conflict with prior findings, namely that the cleavage of Myo1f by the cancer-promoting Tasp1 prevents Myo1f-induced filopodia formation, which would admittedly avert the acceleration of metastatic processes." (PMID 35601920, 2022). "MYO1F, SASH3 and KLHL41 are the candidate pathogenic genes that shared with multi-cancers in this paper." (PMID 31888692, 2019). "Activation of STAT3 by mTORC1 promotes survival and cancer stem-like cell properties a phenotype not observed in macrophages expressing Myo1F." (PMID 30687322, 2018).
infection (6 papers, 2017 to 2025). The state of being infected such as from the introduction of a foreign agent such as serum, vaccine, antigenic substance or organism. "Myo1f-deficient neutrophils show a severely impaired migration rate on fibronectin and Myo1f-deficient mice are more susceptible to infection." (PMID 35601920, 2022). "Indeed, Myo1f knockout mice showed increased susceptibility to infection by Listeria monocytogenes due to an improper neutrophil migration to the infection sites." (PMID 31143189, 2019). "Interestingly, Myo1f knockout mice have also been reported to show increased susceptibility to infection by Listeria monocytogenes as a consequence of abnormally increased adhesion and reduced motility of neutrophils." (PMID 31143189, 2019). "In recent findings, MYO1F was identified as critical for immune cell motility and innate host defense against infection with Listeria monocytogenes." (PMID 34301894, 2021). "Another key component in the immune system expressing a circRNA in neutrophils is MYO1F, a class I myosin regulating the host defense against infection." (PMID 28842720, 2017). "Finally, given evidence Myo1f expression during secondary infection, we tested for a role for this gene in Th1-recall 3-days after re-infection." (PMID 40132035, 2025). "MYO1F (Myosin IF) is mainly expressed in neutrophils, and molecular experiments in mice have demonstrated that this gene may help neutrophils fight infection and that it plays a critical role in acute and chronic inflammatory diseases." (PMID 36344742, 2022). "Given prior evidence of Myo1f’s role in regulating movement and granule exocytosis in innate immune cells, particularly neutrophils, we hypothesized that this myosin protein might also control T cell migration and function during infection." (PMID 40132035, 2025). "After re-infection, expression of Myo1f and Prr13 was retained, without evidence of further up-regulation in PbTIIs (Fig 1Ci-ii) or polyclonal cells (Fig 1Di-ii)." (PMID 40132035, 2025). "There were no significant changes in terms of Th17 or Th1 cell abundance in the lymph nodes or spleens between WT and Myo1f-KO mice in the absence of infection." (PMID 34301894, 2021). "Similarly, upregulation of IFNγ or CXCR6 upon re-infection proceeded normally in the absence of Myo1f (Fig 7Ci-ii)." (PMID 40132035, 2025).
neurodegenerative disease (3 papers, 2019 to 2025). A disorder of the central nervous system characterized by gradual and progressive loss of neural tissue and neurologic function. "Additionally, systems biology analysis suggests that MYO1F is one of the seven microglia-specific genes potentially involved in a shared molecular pathway underlying the human ageing process and multiple neurodegenerative diseases such as AD, Parkinson's disease and Huntington's disease." (PMID 41208482, 2025).
MYO1F also shares sentences with these, for which no sentence is quoted: amyotrophic lateral sclerosis (1 paper); autoimmune disease (1); colorectal cancer (1); Crohn's colitis (1); diabetes (1); duodenitis (1); E. coli infection (1); frontotemporal dementia (1); Hypertension (1); inflammatory bowel disease (1); liver fibrosis (1); neurological disorders (1); non-Hodgkin lymphoma (1); ovarian carcinoma (1); schistosomiasis (1); systemic lupus erythematosus (1); type 2 diabetes mellitus (1); viral myocarditis (1).